KCNK3 (potassium two pore domain channel subfamily K member 3)
Diseases named in the same sentence as KCNK3 in open-access papers (continued):
Sharing a sentence is not in itself a finding about the gene and the disease.
idiopathic pulmonary arterial hypertension (3 papers, 2014 to 2023). A sporadic form of pulmonary arterial hypertension (PAH) characterized by elevated pulmonary arterial resistance leading to right heart failure. "However, it’s worth noting that some research indicates an association between the new gene KCNK3 and familial and idiopathic pulmonary arterial hypertension, potentially elevating pulmonary artery pressure." (PMID 38028487, 2023). "Furthermore, KCNK3 loss-of-function mutations were found to cause idiopathic pulmonary arterial hypertension and acute pharmacological K2P3.1 (TASK-1) inhibition in pigs led to a mild but significant increase in invasively measured pulmonary arterial pressure." (PMID 34831137, 2021). "In addition, just recently, multiple mutations in the acid-sensitive K2P channel TASK-1 (KCNK3) were reported to cause familial and idiopathic pulmonary arterial hypertension." (PMID 24972929, 2014).
glioma (2 papers, 2023 to 2024). A benign or malignant brain and spinal cord tumor that arises from glial cells (astrocytes, oligodendrocytes, ependymal cells). "KCNK3, a member of the K+ channel protein family, has demonstrated significance in glioma growth, particularly given its extensive expression in the nervous system." (PMID 38534332, 2024).
ischemic stroke (2 papers, 2010). A stroke disorder caused by obstruction of blood flow to the brain, due to thrombotic (local blood clot formation) or embolic (due to a blood clot or other material traveling from another site) event. "The TASK subfamily of channels, notably TASK-1 (KCNK3) and TASK-3 (KCNK9), have now been shown to modulate inflammation and neurodegeneration in EAE and probably also ischemic stroke, thus identifying new potential molecular targets for the therapy of inflammatory and degenerative CNS disorders." (PMID 20356357, 2010).
Primary hyperaldosteronism (2 papers, 2016 to 2022). A form of hyperaldosteronism caused by a defect within the adrenal gland. "Our identification and independent replication of variants in KCNK3, a gene implicated in primary hyperaldosteronism, as well as a variant in HOTTIP (HOXA-EVX1) suggest that further work to clarify the roles of these genes may be warranted." (PMID 27736895, 2016).
brain glioblastoma (1 paper, 2020). A WHO grade IV malignant astrocytic tumor that arises from the brain, usually the cerebral hemispheres. "In a related study, KCNK1, KCNK3, and KCNK10 were significantly downregulated in brain glioblastoma (GBM)." (PMID 32906679, 2020).
cardiomyopathy (1 paper, 2021). A disease of the heart muscle or myocardium proper. "In addition to its role in the control of heart rhythm, K2P3.1 (TASK-1) is also discussed as a regulator of cardiac energetics and metabolic function, as Kcnk3 knockout mice were protected from pressure overload-induced cardiomyopathy." (PMID 34831137, 2021).
familial pulmonary arterial hypertension (1 paper, 2022). "Previous studies showed that KCNK3 channels were involved in regulations of pulmonary arterial pressure, and aberrant expression of KCNK3 has been determined as a rare factor for idiopathic and familial pulmonary arterial hypertension." (PMID 35963847, 2022).
long QT syndrome (1 paper, 2026). "This included genetic variants spatially interacting with AFIB and long QT syndrome-associated genes such as KCNK3 and NOS1AP53,54." (PMID 41526351, 2026).
scleroderma (1 paper, 2020). Scleroderma is a rare autoimmune connective tissue disorder characterized by abnormal hardening of the skin and, sometimes, other organs. "Further experiments are needed to investigate the contribution of KCNK3 in scleroderma-associated PH." (PMID 32882918, 2020). "The contribution of KCNK3 dysfunction in scleroderma-associated PH is unknown; however, we could hypothesize that RELM-β overexpression should reduce KCNK3 expression in the lungs of scleroderma-associated PH patients." (PMID 32882918, 2020).
thyroid cancer (1 paper, 2020). "Interestingly, the results that the low mRNA levels of KCNK2 and KCNK3 were related to longer overall survival in thyroid cancer patients was inconsistent with different analyses of the UALCAN database, which showed low KCNK2 and KCNK3 expression in thyroid cancer." (PMID 32742463, 2020).
viral infection (1 paper, 2020). "IFIT genes are involved in the response to viral infection as well as KCNK3." (PMID 33036472, 2020). "The reduced expression of interferon-signaling proteins suggest that, in the absence of KCNK3, hPASMCs and hPAECs should have a drop in their viral infection response." (PMID 33036472, 2020).
cancer (18 papers, 2012 to 2026). A tumor composed of atypical neoplastic, often pleomorphic cells that invade other tissues. "The correlation heatmap showed that PDE2A was positively associated with SEMA6B, RUNDC3B, MICU3, and KCNK3 genes in the majority of cancers." (PMID 39699377, 2024). "The identification of SEMA6B, RUNDC3B, MICU3, and KCNK3 as top PDE2A-correlated genes provided novel targets for functional validation studies aimed at elucidating the molecular mechanisms underlying PDE2A's role in cancer." (PMID 39699377, 2024). "The differentially expressed proteins in KCNK3-knockdown hPAECs were associated with 19 functional networks, including protein synthesis, molecular transport (network 1) and RNA post-transcriptional modification, and cancer (network 2)." (PMID 33036472, 2020). "The differentially expressed proteins in KCNK3-knockdown hPASMCs were associated with 12 functional networks, including RNA post-transcriptional modification, cancer, hematological disease (network 1), RNA damage and repair, protein synthesis, gene expression (network 2)." (PMID 33036472, 2020). "TASK-1, encoded by the KCNK3 gene, is emerging as a putative target in cancer; it regulates resting membrane potential, cell proliferation, and apoptosis." (PMID 42123646, 2026). "A three-gene signature model (KCNK3, AK5, and ARHGEF38) was established, and the model was significantly associated with cancer-related pathways, overall survival (OS), and tumor microenvironment (TME)-related immune cells in PCa." (PMID 35372462, 2022). "Moreover, KCNK3 has been proved to be related to multiple kinds of cancer including neuroblastoma, pancreatic cancer, colorectal cancer, and hepatocellular carcinoma." (PMID 35963847, 2022). "To investigate the expression of KCNK3 in LUAD, we first identified gene expression profiles of KCNK3 between cancer and normal tissues through a database-mining approach." (PMID 35963847, 2022). "A three-gene signature model (KCNK3, AK5, and ARHGEF38) was constructed, and the model was significantly related to cancer-related pathways, overall survival, and TME cells in PCa." (PMID 35372462, 2022). "The data show that mRNA expression of KCNK1, KCNK7, and KCNK9 is upregulated in cancer tissues while KCNK2, KCNK3, KCNK5, KCNK10, KCNK13, KCNK15, and KCNK17 levels are decreased compared to controls." (PMID 31581133, 2019). "Although the effects of KCNK3 on NSCLC have been reported, its anti-cancer potential and underlying mechanism on LUAD have not yet been investigated." (PMID 35963847, 2022).
tumor (12 papers, 2018 to 2026). "Transcriptomic profiling and an RNA interference-based rescue screen identified KCNK3, a putative tumor suppressor, as a key mediator of DNMT inhibitor-induced synthetic lethality in VHL-deficient RCC." (PMID 41792232, 2026). "KCNK3 has been shown to influence apoptosis and proliferation in NSCLCs, and KCNK3 knockdown increases apoptosis in tumor cells." (PMID 35676660, 2022). "The potential tumorigenicity of KCNK3 on LUAD in vivo was validated in a mouse xenograft tumor model." (PMID 35963847, 2022). "Studies on cBioportal were analyzed for mutation frequencies of GPR31, GPR151, KCNK3, and KCNK9 in the investigated tumor entities." (PMID 35011589, 2021). "Additionally, the tumor weight and volume of KCNK3-OE group were remarkedly decreased compared with control group." (PMID 35963847, 2022). "In the 508 primary LUAD tissues and 59 normal samples originated from the Cancer Genome Atlas (TCGA), we found that KCNK3 was significantly downregulated in different clinical stages of LUAD tissues compared with non-tumor tissues, especially in stage I LUAD patients." (PMID 35963847, 2022). "Moreover, our research verified that KCNK3 acted as a putative tumor suppressor and suppressed LUAD cell proliferation and glucose metabolism by targeting AMPK-TXNIP pathway." (PMID 35963847, 2022). "In association with these deregulated pathways, the IPA identified abnormal biological functions, such as the cell spreading and shape change of tumor cell lines, and cell movement, cell attachment, and cell death were found to be significantly activated in KCNK3-knockdown hPASMCs." (PMID 33036472, 2020). "Representative images demonstrated that upregulation of KCNK3 lead to decreased staining intensity of Ki67, GLUT1, and LDHA in the resected tumor when compared with the control group." (PMID 35963847, 2022). "On the other hand, mRNA levels of KCNK3, KCNK13, KCNK15, and KCNK17 correlated positively with tumor differentiation." (PMID 31581133, 2019). "Furthermore, immunohistochemical staining was applied to evaluate the expression of KCNK3, proliferation marker Ki67, and the glucose metabolism GLUT1/LDHA in tumor tissue sections." (PMID 35963847, 2022). "Likewise, the tumor cells lacked expression of the common PNEC mechanosensor PIEZO2 but showed broad expression of the acid-sensitive channel KCNK3 and opsin OPN1SW, which is expressed only by rare normal PNECs." (PMID 36469459, 2022).
infection (6 papers, 2012 to 2025). The state of being infected such as from the introduction of a foreign agent such as serum, vaccine, antigenic substance or organism. "HIV-1 regulates miR-21, which is known to downregulate the KCNK3 expression, allowing a stronger infection efficiency." (PMID 33036472, 2020). "Following infection, let-7c, miR-34a or miR-124a were upregulated, and they targeted and downregulated p21 and TASK1 (also known as CDKN1A and KCNK3, respectively) cellular proteins." (PMID 25717002, 2015).
cardiovascular diseases (4 papers, 2015 to 2026). "Coexpression networks showed several key genes in these cardiovascular diseases, for example, KCNK3, TNNI3, and ELN." (PMID 34003819, 2021). "Broilers are known to suffer from cardiovascular disorders, which may be related to the KCNK3 gene." (PMID 26607727, 2015).
KCNK3 also shares sentences with these, for which no sentence is quoted: cardiac arrhythmia (6 papers); Obesity (5); cardiac hypertrophy (4); Cerebral ischemia (4); HIV-1 infection (4); non-small cell lung carcinoma (4); paroxysmal AF (4); epilepsy (3); heart failure (3); Hypokalemia (3); multiple sclerosis (3); temporal lobe epilepsy (3); adenoma (2); Arrhythmia (2); autoimmune disease (2); Birk-Barel syndrome (2); epileptic seizures (2); essential hypertension (2); heart disease (2); hypertrophy (2); ischemia (2); neurological disorders (2); oral squamous cell carcinoma (2); osteosarcoma (2); ovarian carcinoma (2); squamous cell carcinoma (2); vitamin D deficiency (2); Abdominal obesity (1); acid-base balance disorder (1); adrenal hyperplasia (1).
A further 56 diseases each share a sentence with KCNK3 in 1 paper.